TECRL (trans-2,3-enoyl-CoA reductase like)
Synonyms: SRD5A2L2; GPSN2L; DKFZp313D0829; DKFZp313B2333; TERL; CPVT3
Tractability: Antibody: UniProt predicts a signal peptide or a membrane-spanning region.
Gene: Protein-coding gene on chromosome 4 (64,275,257 to 64,409,495, reverse strand). Ensembl gene ENSG00000205678.
Subcellular location: Membrane; Endoplasmic reticulum
Pathways (Reactome):
Metabolism: Synthesis of very long-chain fatty acyl-CoAs
Gene Ontology:
Molecular function: very-long-chain enoyl-CoA reductase activity; oxidoreductase activity, acting on the CH-CH group of donors
Biological process: very long-chain fatty acid biosynthetic process; lipid metabolic process
Cellular component: endoplasmic reticulum; membrane
Genetic constraint (gnomAD): Loss-of-function variants: 16 observed, 15.47 expected, observed/expected ratio (o/e) 1.03, 90% interval 0.7 to 1.56. The upper end of that interval is the gene's LOEUF score, 1.56, which puts it in group 6 of 6, group 1 being the genes least tolerant of losing a copy. Missense variants: 268 observed, 235.17 expected, observed/expected ratio (o/e) 1.14, 90% interval 1.03 to 1.26. Synonymous variants: 84 observed, 86.8 expected, observed/expected ratio (o/e) 0.97, 90% interval 0.81 to 1.16.
Gene-disease validity (ClinGen):
ClinGen rates the evidence that TECRL causes each of these diseases.
catecholaminergic polymorphic ventricular tachycardia (autosomal recessive): Definitive. Catecholaminergic polymorphic ventricular tachycardia (CPVT) is a severe genetic arrhythmogenic disorder characterized by adrenergically induced ventricular tachycardia (VT) manifesting as syncope and sudden death.
Homologues: Orthologues: chimpanzee TECRL (99% identical), macaque TECRL (98% identical), pig TECRL (89% identical), guinea pig TECRL (84% identical), rat Tecrl (82% identical), mouse Tecrl (82% identical), rabbit TECRL (80% identical), Caenorhabditis elegans art-1 (33% identical), Drosophila melanogaster Sc2 (32% identical). Paralogues in human: TECR (43% identical), SRD5A2 (15% identical), SRD5A1 (14% identical).
Diseases named in the same sentence as TECRL in open-access papers:
TECRL is named in the same sentence as 13 diseases in open-access papers, as found by Europe PMC text mining. Sharing a sentence is not in itself a finding about the gene and the disease. The quoted sentences say what the papers report.
Arrhythmia (5 papers, 2016 to 2025). Any cardiac rhythm other than the normal sinus rhythm. "In the current study, we used WES to identify TECRL as a novel life‐threatening inherited arrhythmia gene associated with a recessive form of inherited arrhythmia with a clinical phenotype that has overlapping features of LQTS and CPVT." (PMID 27861123, 2016). "Taken together, the clinical, genetic, and experimental results from this study have identified TECRL as a new gene associated with life‐threatening inherited arrhythmias displaying features of both LQTS and CPVT." (PMID 27861123, 2016). "The authors have provided compelling data linking homozygous loss‐of‐function mutations in TECRL to the pro‐arrhythmia phenotype in this Sudanese family." (PMID 27784710, 2016). "Here, we presented the clinical phenotype of patients from three different families with exercise‐induced arrhythmias and identified mutations in the gene, TECRL by whole‐exome sequencing." (PMID 27861123, 2016). "In summary, we report that mutations in TECRL are associated with inherited arrhythmias characterized by clinical features of both LQTS and CPVT." (PMID 27861123, 2016). "Further studies are necessary to elucidate the role of TECRL in lipid metabolism and how mutations are linked to cardiac arrhythmias." (PMID 27861123, 2016). "Abnormal fatty acid oxidation is directly associated with arrhythmogenesis, which may explain how TECRL mutations contribute to the development of cardiac arrhythmias." (PMID 40453219, 2025). "It is established that mutation of the critical pathogenic gene TECRL could lead to CPVT, which is associated with Ca2+ processing and the development of arrhythmia." (PMID 38283583, 2024).
catecholaminergic polymorphic ventricular tachycardia (4 papers, 2016 to 2024). "We report two novel pathogenic variants in the TECRL gene associated with recessive catecholaminergic polymorphic ventricular tachycardia and extend on the clinical features associated with this rare genetic variant." (PMID 38777371, 2024). "Pathogenic and likely pathogenic variants in the TECRL gene are known to be associated with recessive catecholaminergic polymorphic ventricular tachycardia 3, which can include prolonged QT intervals (MIM#614021)." (PMID 38777371, 2024). "Mutation in TECRL, an endoplasmic reticulum protein, was first reported in catecholaminergic polymorphic ventricular tachycardia during which a patient succumbed to SCD." (PMID 35577932, 2022). "A third patient from a consanguineous Sudanese family diagnosed with catecholaminergic polymorphic ventricular tachycardia (CPVT) had a homozygous splice site mutation (c.331+1G>A) in TECRL." (PMID 27861123, 2016). "Likely pathogenic and pathogenic variants in TECRL are associated with catecholaminergic polymorphic ventricular tachycardia (CPVT), type 3." (PMID 38777371, 2024). "Our study demonstrated that TECRL mutations are associated with a complex clinical phenotype with characteristics of both long QT syndrome (LQTS) and catecholaminergic polymorphic ventricular tachycardia (CPVT)." (PMID 27861123, 2016).
cardiac arrest (2 papers, 2016 to 2024). Cessation of breathing and/or cardiac function. "Overall, we describe two novel variants in the TECRL gene on chromosome 4q13.1 associated with ventricular tachycardia and cardiac arrest in a previously asymptomatic patient." (PMID 38777371, 2024). "Therefore, we recommend that a homozygous mutation in TECRL should be considered as a possible cause of the etiology in patients presenting with stress‐induced complex ventricular arrhythmias or cardiac arrest at a young age, whether they are diagnosed with (gene‐elusive) LQTS or CPVT." (PMID 27861123, 2016).
sudden cardiac arrest (2 papers, 2024 to 2025). Unexpected rapid natural death due to cardiovascular collapse within one hour of initial symptoms. "Altogether, this case identified novel variants in TECRL associated with CPVT leading to sudden cardiac arrest and extended the clinical features associated with TECRL variants." (PMID 38777371, 2024).
heart failure (1 paper, 2022). Inability of the heart to pump blood at an adequate rate to meet tissue metabolic requirements. "In conclusion, we revealed that TECRL deficiency amplifies oxidative stress, results in loss of mitochondria ultrastructure and function, which is a hallmark of heart failure and aging." (PMID 35577932, 2022).
idiopathic ventricular fibrillation (1 paper, 2024). "Genetic testing is recommended for CPVT-susceptibility genes—RyR2, CASQ2, CALM1-3, TRDN and TECRL—in all probands with a definitive clinical diagnosis of CPVT and may be considered in individuals with idiopathic ventricular fibrillation (VF) upon identification of an adrenergic trigger." (PMID 38542006, 2024).
polymorphic ventricular tachycardia (1 paper, 2024). A ventricular tachycardia that is irregular in rate and rhythm. "And the TECRL was positively correlated with genes involved in the metabolism of fatty acids in BrS patients, which is a disorder also characterized by polymorphic ventricular tachycardia." (PMID 38283583, 2024).
TECRL also shares sentences with these, for which no sentence is quoted: cardiac arrhythmias (2 papers); infection (2); Ventricular arrhythmia (2); epilepsy (1); ventricular fibrillation (1); ventricular tachycardia (1).